TBK1 (TANK binding kinase 1)
Diseases named in the same sentence as TBK1 in open-access papers (continued):
Sharing a sentence is not in itself a finding about the gene and the disease.
cancer (continued). "However, mechanistic evidence for TBK1-mediated NF-κB engagement in cancer has been sparse." (PMID 23209807, 2012). "TANK-binding kinase 1 (TBK1) is essential for oncogenic KRAS-induced cell transformation and maintains the survival of KRAS-dependent cancer cells." (PMID 41184283, 2025). "TANK-binding kinase 1 (TBK1) plays an important role in the innate immune system and is involved in the development of several cancers." (PMID 40478370, 2025). "The results indicated significant upregulation of LAMP2A in cancer tissues compared to adjacent normal tissues, accompanied by decreased expression of STING and TBK1, which was in line with our findings from in vivo experiments." (PMID 40083918, 2025). "ALTO itself or a small molecule mimic of its TBK1 activating domain could serve as a noncanonical TBK1 agonist for boosting antiviral immunity in immunocompromised individuals, potentially suppressing MCPyV replication and reducing cancer risk." (PMID 41277846, 2025). "Further analysis has revealed that STING and TBK1 are direct substrates of CMA, uncovering a novel mechanism for controlling the expression of these two cancer-related proteins." (PMID 40083918, 2025). "Further analysis of the RNA-Seq pathway data revealed that pathways involved in cancer stem cell mechanisms were lost with both ERK inhibition and with the TBK1–IKKε inhibitor." (PMID 40738190, 2025). "The anti-cancer effects of Amlexanox have been attributed to the inhibition of IKBKE and TBK1 but also to the inhibition of other proteins like FGF-1 and S100 proteins." (PMID 40468448, 2025). "This, in turn, triggers conformational changes in STING, activating TANK-binding kinase 1 (TBK1), which phosphorylates IFN regulatory transcription factor 3 (IRF3) and promotes type I IFN expression in cancer cells or antigen presenting cells." (PMID 40342534, 2025). "The ability of TBK1 inhibition to modulate multiple signals, including AKT and NF-κB, underscores its potential as a multi-target anti-cancer approach." (PMID 39744441, 2025). "All cancer cell lines as well as Nuli-1 showed phosphorylation of STING, TBK1, and IRF3 after stimulation with HT-DNA, indicating an active signaling pathway." (PMID 40012911, 2024). "Given the involvement of TBK1 in YAP regulation and the importance of TBK1 in cancer pathogenesis, it will be exciting to determine how the functional interplay between GEF-H1 and TBK1 impacts cancer cell behaviour and tumourigenesis." (PMID 38607079, 2024). "Activated STING is palmitoylated and phosphorylated to recruit TBK1 and IKK, among which TBK1 triggers the release of IFN (a pivotal pathway in cancers, particularly HCC) by activating IRF3, while IKK induces inflammation by activating NF-κB." (PMID 38807595, 2024). "It will be an important issue to understand how the balance of the two mechanisms of TBK1-mediated regulation of BACH1 is coordinated or switched in the context of iron metabolism, hematopoiesis and immune response, and cancer progression." (PMID 38673728, 2024). "In addition to supporting cancer cell survival, the RalB/Sec5/TBK1 cascade is also required for IRF3 nuclear translocation and Sendai virus-induced IFN-β promoter activation, suggesting that RalB/Sec5 effector complex, as an oncogenesis driver, could also be part of innate immune signaling." (PMID 39279883, 2024). "Mutations or abnormal expression levels of specific genes in the RLR signaling pathway, such as MAVS, TBK1, and IRF3, can lead to changes in the immune signaling pathway, resulting in a decreased ability of immune cells to recognize and clear malignant tumors." (PMID 38099311, 2023). "We also observed that TRIM28 expression is positively correlated with PD-L1, TBK1, and IRF1 levels in various cancers." (PMID 37357254, 2023).
cancer (continued). "We assessed the expression of TTK and TBK1 mRNAs using the METABRIC database, using the cBioPortal for Cancer Genomics, an open-access resource for multidimensional cancer genomics datasets analysis tool." (PMID 36494865, 2022). "For example, in many human cancer cell lines and mouse embryonic fibroblasts, activated K-RAS triggers TBK1 autophosphorylation on Ser172 by recruiting TBK1 to the exocyst where TBK1 appears to complex with Sec5 and RALB GTPases." (PMID 35395857, 2022). "We then analyzed a smaller cohort of TNBC patients from Moffitt Cancer Center (N = 129) for the expression of TTK, active (p-TBK1), Ki-67, Vimentin, and E-cadherin in NHB and NHW patients." (PMID 36494865, 2022). "The innate immune STING signal defends against viruses and cancers potently and rapidly, accompanied by the phosphorylation of the transcription factor IRF3 by kinase TBK1 and then the production of type I IFNs." (PMID 34299262, 2021). "These channels allow the transfer of the second messenger, cGAMP, from cancer cells to adjacent astrocytes to activate STING, thereby triggering TBK1 and IRF3 and producing IFN-α and TNF-α." (PMID 35046953, 2021). "In human cancer cell lines (HeLa, UPN251, and HOC1), PARPi treatment leads to cytosolic DNA accumulation and activates downstream signaling molecules TBK1 and IRF3." (PMID 34367175, 2021). "The cGAS-STING, TBK1, and IRF3 increasingly express in pan-cancer cells, and their gene expression level negatively correlates with their methylation in most cancer types." (PMID 33643304, 2020). "TBK1 is a constituent of the RAL pathway and is crucial to the induction and progression of RAS-driven cancers." (PMID 31681587, 2019). "Treatment of KPC1242 cancer cells with DMXAA, alone or in combination with gemcitabine, increased phosphorylation of TBK1 and STAT6, two cardinal STING signaling pathways." (PMID 31036082, 2019). "Consequently, JAK2 and TBK1 inhibitors may have utility in this cancer." (PMID 30105668, 2019). "Our in vivo data showed that a TBK1 inhibitor alleviates RIPI and protects mice against IR, providing a novel strategy for preventing RIPI during cancer radiotherap." (PMID 30988282, 2019). "Based on this, it is likely that conclusions regarding TBK1 sensitivity in KRAS-positive cells, as well as other cancers, will be dependent on factors that relate to the differentiation status of the cells in question." (PMID 30223576, 2018). "Various mitophagy effectors have been shown to be defective in human cancers, including PINK1, Parkin, Optn, p62, TAX1BP1, NIX (BNIP3), and TBK1." (PMID 29971063, 2018). "While primarily studied for their roles in innate immune response, the IκB kinase (IKK)-related kinases TANK-binding kinase 1 (TBK1) and IKKε also promote the oncogenic phenotype in a variety of cancers." (PMID 30223576, 2018). "Both syntenin-1 and TBK1 have been reported to be upregulated in multiple cancer types and contribute to cancer progression, but none has related those two genes in cancer development." (PMID 40412527, 2025). "When compared to the control medium, the conditional media of lamin-deficient cancer cells did not change NLRP3 inflammasome and STING/TBK1 pathways in macrophage cells." (PMID 40708945, 2025). "The activation of TBK1 in NSCLC may exacerbate these processes, potentially linking syntenin-1 phosphorylation to the progression of this cancer type." (PMID 40412527, 2025). "In NSCLC, TBK1 is a key factor in the KRAS-induced oncogenic transformation of mouse embryonic fibroblasts; the activation of TBK1 by upstream signaling inhibits the apoptosis of cancer cells." (PMID 40076567, 2025).
cancer (continued). "Elevated expression of TBK1 has been reported in many different types of cancer with high expression correlated with negative patient outcomes." (PMID 38059900, 2024). "TBK1 functions as a central node for several innate immune pathways, including the POLIII/RIG-I/MAVS pathway, which is required for radiation-induced T1IFN expression in some cancer types." (PMID 38376927, 2024). "EV MDA5 agonism has an intriguing innate footprint, characterized by polar TBK1-IFN regulatory factor 3 (IRF3) signaling, which fuels sustained type-I IFN release to provide context for antitumor CD8+ T-cell priming after in situ cancer vaccination." (PMID 37962360, 2023). "Taken together with these reports, our findings suggested that TBK1 may promote EMT and metastasis of cancer cells via both BACH1-independent and BACH1-dependent mechanisms." (PMID 36009179, 2022). "Our analysis of mutation rates showed that the four STING pathway genes (cGAS, STING, TBK1 and IRF3) were usually not mutated in human cancers, with a complete absence of homozygous loss-of-function mutations in almost all cancer types." (PMID 35794238, 2022). "Furthermore, TBK1 can also be activated by inflammatory cytokines including APRIL, BAFF, IL-1, and IL-17, as well as by activated K-RAS in cancer cells, as will be discussed in later sections." (PMID 35395857, 2022). "In experiments on human cancer cell lines, the lack of TBK1 induced apoptosis which was specifically dependent on oncogenic KRAS expression." (PMID 34944712, 2021). "Non-canonical IκB kinases (IKKs) TBK1 and IKKε have essential roles as regulators of innate immunity and cancer." (PMID 30791439, 2019). "While TBK1 and IKKε inhibitors have been developed and used in several cell-based studies and animal models, no clinical trials have been initiated related to cancer." (PMID 30223576, 2018). "The phosphorylated TBK1 and IKK stimulate the transcription factors interferon nuclear factor κB (NF-κB) and interferon regulatory factor 3 (IRF3), eliciting the expression of proinflammatory cytokines such as interleukin 6 (IL-6) and type I interferons (IFN-I) to kill cancer cells." (PMID 38999073, 2024). "In these cancers, TBK1 activity is positively correlated with disease progression thus serving as an indicator of poor prognosis, specifically in those tumors harboring activated K-RAS/N-RAS, suggesting TBK1 functions as an oncoprotein at least in these cancer types." (PMID 35395857, 2022). "Therefore, the results suggested that TBK1-regulated inflammatory cytokines may promote the immunosuppressive microenvironment of HCC, as a clear example of inflammation-related cancer." (PMID 33679751, 2021). "Another group observed that TBK1 is active in mutant NRAS melanoma and promoted migration and invasion of these cells, suggesting that RAS-driven epithelial plasticity may be active in the presence of other RAS isoform-driven cancers." (PMID 31681587, 2019). "In this case, TBK1 did not regulate Akt phosphorylation in HER2+ cancer cells." (PMID 30223576, 2018). "The studies on cancer-associated chromosomal instability and STING signaling need to include methods other than measurement of phosphorylation of IRF-3 in order conclude that TBK1 is not involved." (PMID 30223576, 2018). "Interestingly, STING expression is often reduced or lost in many cancers, suggesting that STING is not driving TBK1/IKKε activation widely in cancers." (PMID 30223576, 2018). "Surprisingly, after the stimulation of cells with IL-1β or TNFα, after mitophagy induction or in cancer dependent on KRAS signaling, TBK1 is phosphorylated whereas IRF3 is not." (PMID 27538435, 2016).
cancer (continued). "The proposed master regulator TBK1 is a member of the non-canonical IκB protein kinases which is involved in the activation of IRF3 and c-Rel and NF-κB in cancer." (PMID 27092172, 2016). "To test if type III IFNs are regulated by TBK1/IKK signaling similar to type I IFNs in response to STING agonism, we treated the cancer cell and PBMC co-cultures with the HER2 ADC with or without TBK1/IKKε inhibitor BX795 and measured IFNβ and IFNλ cytokine production." (PMID 38992037, 2024). "Interestingly, STING, TBK1, and IRF3 were not phosphorylated after transfection with 3′3′-cGAMP in these cancer cell lines." (PMID 33490069, 2020).
neurodegenerative disease (27 papers, 2015 to 2025). A disorder of the central nervous system characterized by gradual and progressive loss of neural tissue and neurologic function. "When testing an additional 94 genes associated with neurodegenerative diseases we identified variants in the amyotrophic lateral sclerosis disease-linked gene TBK1 associated with T1R (P = 0.004; OR = 12.9)." (PMID 41430073, 2025). "Amyotrophic lateral sclerosis and frontotemporal dementia are neurodegenerative diseases with a common genetic susceptibility, with the development of both conditions having been associated with TBK1 dysregulation." (PMID 36849530, 2023). "The protein kinase TBK1 is a central regulator of innate immune responses and autophagy, and ablation of either function has been linked to neuroinflammatory or degenerative diseases." (PMID 34226595, 2021). "TBK1-mediated regulation of autophagy is currently under evaluation because TBK1 haploinsufficiency is a major risk factor in neurodegenerative diseases." (PMID 29559975, 2018). "Together, our findings are valuable for understanding the functions of OPTN and TBK1 in selective autophagy, as well as the pathogenesis of neurodegenerative diseases caused by mutations of OPTN and TBK1." (PMID 27620379, 2016). "Mutations in optineurin that cause defects in the interaction with TBK1 are associated with neurodegenerative diseases." (PMID 27620379, 2016). "Potential risks of TBK1 inhibition have been raised, such as increased susceptibility to infections, as well as a link between heterozygous loss-of-function mutations in TBK1 with neurodegenerative diseases." (PMID 40341181, 2025). "For loss-of-function TBK1 alleles, gene-replacement approaches that provide a functional TBK1 transgene via viral vectors are conceptually simple and have been explored in other neuromuscular and neurodegenerative diseases." (PMID 41302089, 2025). "Importantly, our structural data also provide mechanistic explanations to why several mutations found in OPTN and TBK1 can cause neurodegenerative diseases." (PMID 27620379, 2016). "Mutations of optineurin and TBK1 are both associated with neurodegenerative diseases." (PMID 27620379, 2016). "Mutations in OPTN have been identified as pathogenic factors in a variety of neurodegenerative diseases, including ALS, and mitophagy is specifically dependent on OPTN and its kinase TANK-binding kinase 1 (TBK1)." (PMID 40002740, 2025). "The collaboration between optineurin and TBK1 in the process of mitophagy has been investigated by several groups due to their involvement in neurodegenerative diseases." (PMID 41567509, 2025). "Genes implicated in both monogenic neurodegenerative disease and risk genes are related to microglia and immune pathways, such as APOE, TREM2, and TBK1, many of which were also identified in our microglial transcriptomic and proteomic data." (PMID 38923692, 2024). "Reduced TAK1 expression due to aging, acting in conjunction with haploinsufficient mutations in TBK1, can activate RIPK1 and trigger aging-related neurodegenerative diseases." (PMID 36849530, 2023). "More than 90 mutations in TBK1 have been linked to ALS, including several mutations identified in patients with the co-occurring degenerative disease, fronto-temporal dementia (ALS-FTD)." (PMID 34099552, 2021). "Exome sequencing identifies TBK1 as a neurodegenerative disease gene in amyotropic lateral sclerosis (ALS) and frontotemporal dementia." (PMID 29559975, 2018). "Researchers investigating the embryonic lethality of Tbk1/ and the neuroinflammation produced by TBK1 reduction involved in multiple neurodegenerative diseases discovered that TBK1 can directly phosphorylate T189/T190, which inhibits RIPK1 in murine species and humans." (PMID 41567509, 2025).
neurodegenerative disease (continued). "The observation that TBK1-E696K mutant that causes ALS-FTD constitutively localizes to lysosomes, phosphorylates Rab7 and enhances mTORC1 amino acid responsiveness strengthens the link between lysosomal TBK1 and mTORC1 activation and suggests a possible neurodegenerative disease relevance." (PMID 39103493, 2024). "Although increasing evidence has shown that mitophagy is protective for neuronal cells in neurodegenerative diseases, including PD and ALS, it is currently still unclear whether induction of mitophagy is beneficial for TBK1-mediated ALS." (PMID 38933121, 2022). "Therefore, restoring Tbk1 function might provide therapeutic benefits for both Tbk1- and SOD1-related neurodegenerative diseases." (PMID 31039129, 2019). "Future analyses of the interactomes of wild-type and mutant SQSTM1, TBK1 and VCP are needed to pinpoint how these proteins cooperate in a common complex with OPTN and UBQLN2 and how alterations in this complex may lead to ALS or other neurodegenerative diseases." (PMID 27164932, 2016).